VIM (vimentin)
Diseases named in the same sentence as VIM in open-access papers (continued):
Sharing a sentence is not in itself a finding about the gene and the disease.
cancer (continued). "Moreover, decreased expression of vimentin has been shown to promote proliferation in cancer cells in vitro and in vivo and corresponds to the increased proliferative profile of HS5-PC3 cells reported here." (PMID 37372146, 2023). "Importantly, TR5‐derived cells exhibited predominant expression of vimentin corroborating the parental mesenchymal tissue phenotype of the cancer cells in TR5." (PMID 36423211, 2023). "HHLA2 knockdown in clear cell renal cell carcinoma (ccRCC) is reported to significantly associated with reduced vimentin and N-cadherin expressions and increased E-cadherin expression, which is indicative of a positive correlation between HHLA2 with cancer stemness profile of cancer." (PMID 38144305, 2023). "It has been reported that vimentin is involved in various types of cancer." (PMID 37717112, 2023). "In cancer-associated EMT, SNAI1 serves as an imperative factor in driving the transition by strongly repressing E-cadherin and tight junction components (claudins), while also upregulating mesenchymal marker proteins, including vimentin and fibronectin." (PMID 38144565, 2023). "In malignant tumors, alterations in epithelial cells are typically marked by the reduction of E-cadherin, an epithelial cell marker protein, coupled with an increase in the expression of N-cadherin, Snail, and Vimentin." (PMID 37573302, 2023). "Hence, targeting extracellular vimentin with the monoclonal 86C antibody induces the apoptosis of glioblastoma multiforme cancer stem cells." (PMID 37475865, 2023). "At the early stage of cancer, when normal cells surround transformed cells, they form arm-like vimentin and generate contractile force to prevent the enclosed transformed cells from forming basal extensions and extrude the transformed cells out from the top of the epithelial monolayer." (PMID 37864030, 2023). "Similar studies evaluating the role of vimentin in fibroblast subpopulations have yet to be established to discern whether these functions are cell or cancer type specific." (PMID 38313431, 2023). "Similarly, methenyltetrahydrofolate cyclohydrolase (MTHFD2) has recently been identified as a novel modulator of the EMT marker vimentin and reported to be a potential pharmaceutical target in advanced cancers." (PMID 37372146, 2023). "Furthermore, we performed double immunofluorescence of Ext1 and vimentin on human cancer stroma, and we confirmed that Ext1-positive fibroblasts were vimentin-positive." (PMID 36809261, 2023). "Furthermore, SCEACono2 exhibited a unique characteristic that cytokeratin, vimentin as well as cancer stem cell markers (CD44, CD133, ALP and Oct3/4) were positive." (PMID 37949965, 2023). "Besides VIM, the basement membrane also promotes cancer cell invasion and metastasis, COL4A1 and COL4A2 are typical basement membranes ubiquitously expressed on cells." (PMID 37642765, 2023). "In addition, epithelial-mesenchymal transition (EMT)-associated marker E-cadherin was repressed, while Vimentin was enhanced in SRC-GOF cells, revealing the potential roles for SRC kinase in cancer stemness and EMT regulations." (PMID 36633714, 2023). "It supports the previous findings that Slug, Vimentin, and N-cadherin play roles in enhancing cancer metastasis and suggests that the pro-metastasis effect of the PZ may involve EMT regulation in the A549 cells." (PMID 37528887, 2023). "Vimentin intermediate filaments orchestrate microtubule patterning and the alignment of traction stresses to allow for directional migration in polypoidal giant cancer cells." (PMID 37612301, 2023). "However, there are studies on actinomycin V which show cytotoxic activity and inhibition of proliferation, invasion, and migration of cancer cells, i.e., processes related to high expression of vimentin and E-cadherin." (PMID 37298856, 2023).
cancer (continued). "Vimentin (VIM) is one of the human intermediate filament proteins and is required for the plasticity of mesenchymal cells under normal physiological conditions and for the migration of cancer cells that have undergone epithelial-mesenchymal transition." (PMID 37642765, 2023). "Over-expression of vimentin in some cancers including CRC has been reported." (PMID 37325423, 2023). "Underlining the current understanding of EMT in cancer research, (high) vimentin expression and absence of E-cadherin determined a fairly migratory phenotype with an elongated shape as was shown for the MDA-MB-231 cell line." (PMID 37175467, 2023). "Additionally, the Western blot analysis revealed that the knockdown of SNHG3 significantly reduced the protein levels of proteins involved in the cell cycle (CDK6, CDK4, and Cyclin D1) as well as cancer metastasis (N-Cadherin, Vimentin, and MMP9)." (PMID 37348024, 2023). "EMT is a pivotal process for the cancer cells to acquire invasive and metastatic potential and the most important hallmarks of this event are downregulation of E-cadherin (epithelial marker) and upregulation of vimentin (mesenchymal marker)." (PMID 36053327, 2023). "Vimentin is at the core of epithelial-mesenchymal transition and metastasis in cancer cells." (PMID 37149651, 2023). "However, in addition to being a marker, vimentin plays an essential role in modulating cancer cell mobility and cancer metastasis since vimentin regulates cell adhesion and spreading." (PMID 36631457, 2023). "Indeed, K17 interacts with HNRNPK and HNRNPS1 proteins have been shown to interact with a type III intermediate filament protein vimentin, which is upregulated in several cancers and plays a critical role in metastasis." (PMID 37592256, 2023). "Vimentin is considered an important marker for EMT in cancer." (PMID 37325423, 2023). "Vimentin and N-cadherin could support cellular integrity and act in several cell signal pathways to modulate the motility and invasion of cancer cells." (PMID 36674747, 2023). "The mechanisms involved in its anti-cancer effects included the reversal of EMT associated with the upregulation of epithelial marker E-cadherin and downregulation of some mesenchymal markers including vimentin, ZEB1 and ZEB2." (PMID 37373500, 2023). "The mechanisms leading to a high level of vimentin expression in cancer cells is worth extensive exploration as this could further our understanding of cancer metastasis and identify new methods to mitigate cancer metastasis." (PMID 36631457, 2023). "However, only a few cells within the neoplastic cell population tested positive for vimentin, aligning with the characteristics of carcinoma." (PMID 38105775, 2023). "The sarcomatoid tumors were all positive with at least two pan-cytokeratin antibodies and considered carcinomas, although some positivity for vimentin could be observed." (PMID 36346458, 2023). "Here, we show that vimentin, a cytoskeletal intermediate filament protein that we have known to be important for wound healing and cancer progression, determines cell size through mTORC1 signaling, an effect that is also manifested at the organism level in mice." (PMID 36099296, 2022). "Furthermore, vimentin, another classic EMT marker, has been revealed as the direct target of withaferin A, which reduces EMT‐associated cancer metastasis by triggering the degradation of vimentin intermediate filaments." (PMID 35601657, 2022). "In addition, vimentin is related to poor prognosis in many types of cancers and is shown to be a downstream effector of the slug signaling pathway that plays a role in EMT progression." (PMID 36230521, 2022). "Moreover, some of these CXCR4+ cells were also positive for human-vimentin expression, implying that they were cancer cells." (PMID 35456719, 2022).
cancer (continued). "Hence, we analyzed TCGA expression data from 32 cancer types (∼9,000 patient samples) to identify LncRNAs associated with EMT markers, VIM, FN1, SNAI1, SNAI2, and CDH1 (and material and method)." (PMID 36120580, 2022). "Interestingly, acetylation status of vimentin regulates the migration and invasion activities in cancer cells." (PMID 35163593, 2022). "Cancer cell undergoes EMT to acquire migratory and invasive properties, which involves loss of epithelial markers such as ZO-1, E-cadherin and increased expression of mesenchymal markers such as N-cadherin, vimentin as well as MMPs." (PMID 36088372, 2022). "The expression of the fluorescence signal was obvious at 6 h after treatment with NK cells, indicating that vimentin and actin filaments of cancer cells may reflect NK cell attack." (PMID 36032170, 2022). "C12, highly expressed ACTA2, VIM, and FGF9, was recognized as cancer-associated fibroblasts (CAFs)." (PMID 35523772, 2022). "There was overexpression of Vimentin in many kinds of cancer cells." (PMID 35281866, 2022). "Therefore, to analyze the cytoskeleton organization of fibroblasts from normal and cancer tissues, we evaluated the presence of intermediate filaments and stress fibers by vimentin immunofluorescence and phalloidin fluorescence staining, respectively." (PMID 35743318, 2022). "Therefore, we found that vimentin was upregulated in highly immunoresistant cancer cells in response to immune cell attack." (PMID 36032170, 2022). "This study unveils a pivotal role for vimentin in the biology of cancer." (PMID 35606362, 2022). "It has been previously reported that LC-derived extracellular vesicles mediate epithelial-mesenchymal transition by the transfer of Vimentin—which we also found to be differentially expressed in SCLC and SqCC—and regulate angiogenesis, activate cancer-associated fibroblasts, and mediate metastasis." (PMID 35681609, 2022). "Additionally, it has been reported that the phosphorylation of vimentin on Ser39 governs cancer metastasis via Akt-dependent signaling pathway." (PMID 35163593, 2022). "It was testified that vimentin was a more vital determinant for cancer metastasis, and study has confirmed that the inhibition of vimentin could suppress the EMT in GC." (PMID 35297303, 2022). "VIM, a multifunctional protein, exhibits interactions with diverse proteins and ascertains itself to be a marker for highly aggressive and metastatic forms of almost all cancers." (PMID 35571016, 2022). "E-cadherin and Vimentin are frequently dysregulated in multiple human cancers." (PMID 35470736, 2022). "Thus, epithelial mesenchymal transition (EMT) marker proteins (SNAIL, fibronectin, E-cadherin, MMP-1, MMP-9 and vimentin) as well as cancer cell migration and invasiveness processes were analyzed in the presence of E2." (PMID 36419896, 2022). "For instance, cell line model studies have shown that a high concentration of fibrinogen can induce epithelial-mesenchymal transition (EMT) by raising the expression of vimentin and decreasing the expression of E-cadherin, thus enhancing the invasion and migration of cancer cells." (PMID 35463340, 2022). "Therefore, a further comparison of the response of vimentin was made between sensitive and resistant cancer cells when attacked by NK cells." (PMID 36032170, 2022). "However, confirmation of the direct link between the hypoxic HDAC6-SMAD3-SARA pathway and the ITGB2/VIM effect on hypoxia-induced cancer cell invasion will require further investigation." (PMID 35681731, 2022). "This process occurs during cancer development, where there is a loss of expression of epithelial-associated molecules like CDH1 and an increase of mesenchymal-associated molecules such as N-cadherin (CDH2), vimentin (VIM), and fibronectin (FN1)." (PMID 34524579, 2022). "The role of vimentin in cancer cell motility, migration and invasion is well established." (PMID 36568154, 2022).
cancer (continued). "After several hour’s irradiation to cancer cells with X-rays, the migration and invasion capacities of these cells were increased, paralleled by a decrease of E-cadherin expression and an increase of Vimentin and Smad3 expression." (PMID 35251963, 2022). "In cancer, CD68+ macrophages located around the tumor core contributed to the EMT process by triggering the downregulation of E-cadherin and the upregulation of vimentin, N-cadherin, and Snail in the epithelial and cancer cells via the release of TGF-β, a process potentially present in IPF as well." (PMID 36232756, 2022). "Meanwhile, the vimentin-positive stromal cells were present in both ERBB2d16 high and low groups, which may largely compromise the differences caused by EMT in cancer cells." (PMID 35463314, 2022). "The new understanding of how the dynamics, solubility and spatial organization of vimentin are linked to cellular contractile forces, cell adhesions, cell migration and cell shape contributes to our understanding of vimentin functions in health and disease, including in cancer metastasis." (PMID 36483676, 2022). "In order to evaluate the effect of RNase A on metastasis development, we investigated the expression of markers associated with epithelial–mesenchymal transition (EMT): Cdh1 (E-cadherin), Tjp1, Fn and Vim (vimentin), which play important roles in cancer invasion and metastasis." (PMID 35745743, 2022). "In fact, mesenchymal-type cancer cells have low expression of epithelial markers like CDH1 and high expression of mesenchymal markers such as CDH2 gene encoding N-cadherin, fibronectin, and vimentin, among others." (PMID 36497132, 2022). "In this context, vimentin is localized to discrete cytoplasmic and membrane compartments in mesenchymal cells, fibroblasts, astrocytes, epithelial cells, cells in lymphoid tissues, glandular cells, and various cancer cell types." (PMID 35359446, 2022). "As N-cadherin and vimentin endow cancer cells with increased migration and invasiveness, their further downregulation might suggest the inhibition of the metastatic potential of the cells." (PMID 37529796, 2022). "The invasion of cancer cells was found to be suppressed by vimentin knockdown strategies." (PMID 35571016, 2022). "Silencing of N-cadherin generates a less invasive and motile phenotype in cancer cell lines along with the down regulation of fibronectin and vimentin and increased expression of the epithelial marker E-cadherin, losing the stem cell-like features of mesenchymal cells." (PMID 36230521, 2022). "We constructed a PPI network via a STRING database to study the interaction between CD24, CD44 as cancer stem cell markers, and vimentin and E-cadherin as epithelial mesenchymal transition markers with a significant expression of the proteomics composition of WHF." (PMID 35735628, 2022). "It is implied from this conclusion that inhibiting the expression of vimentin in resistant cancer cells may enhance the cytotoxicity of immune cells." (PMID 36032170, 2022). "Although there are numerous reports correlating the expression of vimentin with cell migration during a wide range of processes including wound repair and cancer metastasis, little is known regarding the specific molecular and cellular changes brought about by vimentin expression." (PMID 36200046, 2022). "Here, we chose this technology to target vimentin by vaccination as a strategy against cancer." (PMID 35606362, 2022). "It remains to be determined whether phosphorylation of Y211 actively induces EMT in cancer cells, hence enhancing the expression of mesenchymal molecules such as αSMA and vimentin." (PMID 35628489, 2022). "In addition, minocycline treatment resulted in an increase in the E-Cadherin level and decreases in the levels of N-Cadherin, Vimentin, Slug and Snail in these cancer cells." (PMID 35414768, 2022).
cancer (continued). "Finally, we also evaluated the labelling of vimentin, a biomarker of mesenchymal cells that is related to increased malignancy of cancer cells." (PMID 35204691, 2022). "Also, researchers found that KIFs help to cross-link vimentin in microtentacles, which are important for cancer metastasis." (PMID 35812733, 2022). "The expression level of vimentin increases during cancer migration and invasion." (PMID 35449812, 2022). "In the stromal compartment, quite a few N+ve cells were also positive for the mesenchymal marker vimentin, suggesting that VSV-GP could infect cancer-associated fibroblasts (n = 7/9)." (PMID 36097280, 2022). "Vimentin, a mesenchymal marker, has recently been reported to be an indicator of the epithelial-to-mesenchymal transition (EMT), associated with migration and metastasis in various cancers as well." (PMID 35625426, 2022). "In line with this hypothesis, previous reports correlate high vimentin expression with restriction of differentiation during development and cancer." (PMID 34996451, 2022). "It was found that EMT had a significant effect in process of cancer cells proliferation, invasion and metastasis, and the significant markers of EMT occurrence are the deficient expression of E-cadherin and elevated expression of N-cadherin and Vimentin." (PMID 35513366, 2022). "We attempted to demonstrate that ZER treatment via targeting the important genes involved in cancer chemoresistances such as vimentin, survivin, and β-catenin could reduce 5-FU resistance in CAFs." (PMID 35449812, 2022). "As vimentin is also expressed in hepatic stellate cells boosting cancer survival." (PMID 37829248, 2022). "High vimentin expression was found when cancer cells were attacked by NK cells." (PMID 36032170, 2022). "The importance of vimentin in cancer progression also makes it an attractive druggable target." (PMID 35766227, 2022). "However, in mamma carcinoma, vimentin was associated with epithelial-to-mesenchymal transition (EMT), a migratory phenotype, increased risk for metastasis, and therefore important for cancer progression." (PMID 35682984, 2022). "Interestingly, partial phosphorylation of vimentin by 14-3-3 can soften the filament to facilitate increased mobility of cancer cells." (PMID 35207438, 2022). "Therefore, the crosstalk between vimentin and AXL plays a key role in vimentin-dependent cancer cell migrations observed during EMT." (PMID 34638469, 2021). "Therefore, we additionally investigated cell adhesion upon vimentin treatment in the present study, which showed that vimentin treatment increased the adhesion strength in MCF-7 cancer cells." (PMID 34299089, 2021). "Therefore, we propose that vimentin should be a therapeutic target using molecular technologies that will curb cancer growth and spread with reduced mortality and morbidity." (PMID 34638469, 2021). "The highest absorbance was shown in NCI-H460 cells expressing phosphomimetics at S339, and the next highest in cells expressing T327E and S83E, indicating that the phosphorylation of vimentin at S339, T327, and S83 promotes cancer invasiveness and cell motility." (PMID 33963314, 2021). "However, most of the reported effects on actin, tubulin and vimentin phosphorylation in cancer cells emerge from studies using kinase-specific drugs." (PMID 36046434, 2021). "The expression of E-cadherin and vimentin was increased and decreased, respectively, after PP treatment, suggesting that PP could reverse the progression of cancer EMT." (PMID 33554313, 2021). "KI67 represents proliferation, and VEGF and Vimentin refer to the invasion of cancer cells." (PMID 34867387, 2021). "Vimentin controls FAK activity through the VAV2-Rac1 pathway in cancer cells." (PMID 34830801, 2021). "For instance, HIF-1α may activate N-cadherin and vimentin to mediate EMT by promoting the loss of cell-cell adhesion which subsequently results in more migratory and invasive cancer cells." (PMID 33546106, 2021).